PTTG2 (pituitary tumor-transforming 2)
Tractability: PROTAC: ubiquitination databases record sites on it.
Gene: Protein-coding gene on chromosome 4 (37,960,398 to 37,961,128, forward strand). Ensembl gene ENSG00000250254.
Subcellular location: Cytoplasm; Nucleus
Subcellular location (Human Protein Atlas): Cytosol; Nucleoli
Gene Ontology:
Molecular function: protein binding; cysteine-type endopeptidase inhibitor activity
Biological process: homologous chromosome segregation; chromosome organization
Cellular component: nucleus; cytoplasm
Genetic constraint (gnomAD): Loss-of-function variants: 2 observed, 0.85 expected, observed/expected ratio (o/e) 2.36. That is too few expected variants to judge how well the gene tolerates losing a copy. Missense variants: 193 observed, 204.87 expected, observed/expected ratio (o/e) 0.94, 90% interval 0.84 to 1.06. Synonymous variants: 77 observed, 74.67 expected, observed/expected ratio (o/e) 1.03, 90% interval 0.86 to 1.25.
Homologues: Orthologues: chimpanzee PTTG2 (92% identical), dog PTTG1 (75% identical), guinea pig Pttg1 (71% identical), mouse Pttg1 (61% identical), rat Pttg1 (61% identical), tropical clawed frog XB5905938 (31% identical), zebrafish pttg1 (27% identical). Paralogues in human: PTTG1 (85% identical).
Diseases named in the same sentence as PTTG2 in open-access papers:
PTTG2 is named in the same sentence as 16 diseases in open-access papers, as found by Europe PMC text mining. Sharing a sentence is not in itself a finding about the gene and the disease. The quoted sentences say what the papers report.
glioblastoma (4 papers, 2021 to 2025). The most malignant astrocytic tumor (WHO grade IV). "PTTG2 has been implicated in glioblastoma tumorigenesis as well as in head and neck squamous cell carcinoma, UTS2 has been reported to possess prognostic value in colorectal and breast cancers, TRAT1 in early breast cancer prognosis and DUSP1 in sarcoma progression." (PMID 39478658, 2025). "For instance, an earlier study demonstrated a significant up-regulation of PTTG2 in glioblastoma, establishing its overexpression as a promoter of glioblastoma cell proliferation and invasion." (PMID 40877987, 2025). "For instance, recent studies showcased a significant up-regulation of PTTG2 expression in glioblastoma, where its overexpression facilitated glioblastoma cell proliferation and invasion." (PMID 39139816, 2024). "Additionally, the overexpression of PTTG2 also inhibits apoptosis in glioblastoma by affecting caspase-3-dependent signaling pathways." (PMID 33845847, 2021).
pituitary tumor (3 papers, 2011 to 2018). A benign or malignant neoplasm affecting the pituitary gland.
breast carcinoma (2 papers, 2020 to 2025). "Our data revealed that “TTP metabolism” was correlated with PTTG1 expression, “glycolysis/gluconeogenesis” was associated with PTTG2 expression, and the “dCTP/dUTP metabolism” pathway was correlated with PTTG3 expression in breast cancer development." (PMID 33173433, 2020). "Our data showed that “glycolysis and gluconeogenesis” were correlated with PTTG2 expression in breast cancer development, which suggests that PTTG2 may regulate TTP signaling in cancer progression." (PMID 33173433, 2020). "The Kaplan-Meier plot database analyzed the overexpression of PTTG2 and its relationship with DMFS of breast cancer patients." (PMID 33173433, 2020). "However, breast cancer patients with basal subtypes had poorer survival times when PTTG2 was overexpressed, but this was not statistically significant (HR=1.57, p=0.085)." (PMID 33173433, 2020). "Overall, DMFS of breast cancer patients was not correlated with PTTG2 overexpression." (PMID 33173433, 2020).
esophageal squamous cell carcinoma (2 papers, 2020 to 2023). Esophageal squamous cell carcinoma (ESCC) is a type of esophageal carcinoma (EC) that can affect any part of the esophagus, but is usually located in the upper or middle third. "High expression levels of PTTG3P, PTTG1, and PTTG2 have been observed in esophageal squamous cell carcinoma (ESCC) patients and cell lines." (PMID 36770654, 2023). "In vitro studies have confirmed that exogenously the overexpression of PTTG3P promotes the transcription of its parental genes PTTG1 and PTTG2 in esophageal squamous cell carcinoma cells." (PMID 32824814, 2020).
lung adenocarcinoma (1 paper, 2025). A carcinoma that arises from the lung and is characterized by the presence of malignant glandular epithelial cells. "In this comprehensive study, we explored the roles of the pituitary tumor-transforming gene (PTTG) family, including PTTG1, PTTG2, and the pseudogene PTTG3P in lung adenocarcinoma (LUAD)." (PMID 40877987, 2025).
pancreatitis (1 paper, 2025). Inflammation of the pancreas. "We further evaluated the expression of KDELC1 and PTTG2 in samples from non‐tumor pancreas, pancreatitis and PDAC tissues from the HD cohort and observed significantly higher expression in PDAC." (PMID 39478658, 2025).
pharynx tumors (1 paper, 2020). "Moreover, the highest upregulation of PTTG3P expression was observed in pharynx tumors compared to oral and larynx locations, and instances of PTTG1 and PTTG2 were significantly upregulated in HNSCC tumor tissues compared with normal samples." (PMID 32824814, 2020).
squamous cell carcinoma (1 paper, 2020). A carcinoma arising from squamous epithelial cells. "Firstly, the expression levels of PTTG3P and two other members of the PTTG family, PTTG1 and PTTG2, were analyzed across twenty-four different cancers, including squamous cell carcinomas, adenocarcinomas and other cancers based on data from the UALCAN database." (PMID 32824814, 2020). "For PTTG2, the highest fold change value was observed in HNSC (1.68), while the lowest in CESC (0.41) in squamous cell carcinomas." (PMID 32824814, 2020).
cancer (9 papers, 2017 to 2025). A tumor composed of atypical neoplastic, often pleomorphic cells that invade other tissues. "For instance, PTTG2 overexpression was found to be associated with enhanced cell proliferation in cancer patients." (PMID 39139816, 2024). "Notably, PTTG2 had already been reported to be associated with the aggressiveness of several cancer entities." (PMID 39478658, 2025). "While there is limited understanding of the biological roles of PTTG2, this protein, along with its associated counterpart, PTTG3P, has been implicated in the development of numerous human cancers." (PMID 40877987, 2025). "In this study, significantly higher mRNA and protein expression of PTTG2 were found in kidney renal clear cell carcinoma tissues, and mRNA expression of PTTG2 was remarkably correlated with patients’ individual cancer stages and tumor grades." (PMID 33845847, 2021). "For PTTG2 the highest fold change value in this group of cancer was obtained for KICH (2.87) and the lowest for LIHL (0.09)." (PMID 32824814, 2020). "In contrast, PTTG2 expression levels correlated with the N-stage of cancer, cancer grade, lymph node neck dissection, angiolymphatic invasion and HPV p16 status." (PMID 32824814, 2020). "For PTTG2, the highest fold change value in this group of cancer was obtained for STAD (1.70) and the lowest for PRAD (0.59)." (PMID 32824814, 2020). "We need to remember that patients with low expressions of PTTG3P, PTTG1 and PTTG2 have cancer." (PMID 32824814, 2020). "Both PTTG1 and PTTG2 have been reported to serve oncogenic functions in human cancers 9, 10, 11, but the role of PTTG3P in GC remains unclear, and this pseudogene has previously been regarded as functionless." (PMID 28631396, 2017). "Our findings from the methylation analysis indicated that PTTG1, PTTG2, and PTTG3P exhibit hypomethylation in LUAD cells, which may underlie their increased expression, emphasizing the role of epigenetic modifications in cancer development." (PMID 40877987, 2025). "Overall, this study highlights the significance of PTTG1 and PTTG2 in LUAD and presents a strong case for their potential as biomarkers and therapeutic targets, offering valuable directions for future cancer research and treatment development." (PMID 40877987, 2025). "Pituitary tumor transforming genes (PTTG1, PTTG2, and PTTG3P) play key roles in the pathogenesis and development of human cancers." (PMID 33845847, 2021). "We revealed mRNA expressions of PTTG1, PTTG2, and PTTG3 which also named as PTTG3P in 20 types of cancers." (PMID 33173433, 2020). "PTTG2 and PTTG3P, being homologous to PTTG1, have roles not fully elucidated, but their confirmed association with human cancer development is acknowledged." (PMID 40877987, 2025). "It proves that PTTG3P, PTTG1 and PTTG2 may function as oncogenes in HNSCC, similarly as was indicated in other cancers." (PMID 32824814, 2020). "Thus, this evidence suggests that PTTG2 may interact with the APC and Aurora-related signaling pathways to regulate cancer progression." (PMID 33173433, 2020). "However, for PTTG2 and PTTG3P, there are no significant changes observed across the stages (F values = 0.611 and 0.773, respectively; p = 0.608 and 0.51), indicating that these genes might not have a strong association with cancer stage progression in LUAD." (PMID 40877987, 2025).
tumor (9 papers, 2011 to 2025). "Of the nine basal‐like‐associated cfRNA markers, five (PTTG2, RPL23AP7, UTS2, KDELC1, and DEGS1) were found to be overexpressed in basal‐like tumor tissue compared with tumors of the classical subtype within the HD tissue cohort." (PMID 39478658, 2025). "A correlation analysis between KDELC1 and PTTG2 revealed a significant positive correlation between the expression of both transcripts in tumor tissue (HD cohort) and serum‐derived cfRNA (NEOLAP cohort)." (PMID 39478658, 2025). "Univariate analysis using the logistic regression model showed that the high expression of PTTG2 and RAD21 was significantly associated with tumor relapse, while low expression of MAD1L1 was associated with tumor relapse (P values < 0.05 for all cases)." (PMID 32596342, 2020). "The cfRNA transcript profiles of both KDELC1 and PTTG2 could successfully predict tumor relapse after surgical resection." (PMID 39478658, 2025). "Analysis of KDELC1 and PTTG2 cfRNA abundance in 20 serum samples from metastatic patients with transcriptome‐defined tumor subtype from the COMPASS trial showed that the AUC for KDELC1 and PTTG2 was 0.64 and 0.69, respectively." (PMID 39478658, 2025). "Simultaneous silencing of the PTTG1, PTTG2, and PTTG3P genes was performed in same MG-63 cells using siRNA to investigate their combined effects on key cellular processes such as cell cycle regulation, tumor growth, and other critical cellular functions." (PMID 39139816, 2024). "Additionally, while PTTG2 and PTTG3P have been linked to tumor development, no prior study, to the best of our knowledge, has delved into their expression patterns and roles in LUAD." (PMID 40877987, 2025). "However, there are few studies on the functions of PTTG2 and PTTG3 in tumor biology." (PMID 33173433, 2020).
PTTG2 also shares sentences with these, for which no sentence is quoted: head and neck squamous cell carcinoma (2 papers); adenocarcinoma (1); osteosarcoma (1); ovarian tumor (1); sarcoma (1); viral infections (1).